SPAG9 (sperm associated antigen 9)
Description:
The JNK-interacting protein (JIP) group of scaffold proteins selectively mediates JNK signaling by aggregating specific components of the MAPK cascade to form a functional JNK signaling module. Regulates lysosomal positioning by acting as an adapter protein which links PIP4P1-positive lysosomes to the dynein-dynactin complex. Assists PIKFYVE selective functionality in microtubule-based endosome-to-TGN trafficking (By similarity).
Synonyms: JIP-4; CT89; HLC-6; JLP; PHET; HSS; KIAA0516; SYD1; HLC6; MGC14967; MGC74461; MGC117291; HLC4; FLJ13450; FLJ14006; FLJ26141; FLJ34602; JIP4; PIG6
Tractability: Small molecule: a structure with a bound ligand is known. PROTAC: ubiquitination databases record sites on it; its protein half-life has been measured.
Gene: Protein-coding gene on chromosome 17 (50,962,174 to 51,120,926, reverse strand). Ensembl gene ENSG00000008294.
Subcellular location: Cytoplasm; Cytoplasm, perinuclear region; Lysosome membrane; Cytoplasmic vesicle, secretory vesicle, acrosome (Isoform 5)
Subcellular location (Human Protein Atlas): Centriolar satellite; Cytosol
Pathways (Reactome):
Developmental Biology: Myogenesis
Gene Ontology:
Molecular function: protein binding; JUN kinase binding; kinesin binding; MAP-kinase scaffold activity; signaling receptor complex adaptor activity; identical protein binding
Biological process: lysosome localization; positive regulation of cell migration; retrograde transport, endosome to Golgi; vesicle-mediated transport; MAPK cascade
Cellular component: centriolar satellite; cytosol; extracellular exosome; lysosomal membrane; cytoplasm; acrosomal vesicle; perinuclear region of cytoplasm
Genetic constraint (gnomAD): Loss-of-function variants: 23 observed, 124.49 expected, observed/expected ratio (o/e) 0.18, 90% interval 0.13 to 0.26. The upper end of that interval is the gene's LOEUF score, 0.26, which puts it in group 1 of 6, group 1 being the genes least tolerant of losing a copy. Missense variants: 973 observed, 1,361.7 expected, observed/expected ratio (o/e) 0.71, 90% interval 0.68 to 0.75. Synonymous variants: 435 observed, 491.64 expected, observed/expected ratio (o/e) 0.88, 90% interval 0.82 to 0.96.
Homologues: Orthologues: chimpanzee SPAG9 (99% identical), macaque SPAG9 (99% identical), dog SPAG9 (97% identical), pig SPAG9 (96% identical), mouse Spag9 (96% identical), rat Spag9 (96% identical), guinea pig SPAG9 (93% identical), rabbit SPAG9 (80% identical), tropical clawed frog spag9 (76% identical), zebrafish SPAG9 (67% identical), zebrafish spag9a (64% identical), Drosophila melanogaster syd (42% identical), and 1 more. Paralogues in human: MAPK8IP3 (59% identical).
Diseases named in the same sentence as SPAG9 in open-access papers:
SPAG9 is named in the same sentence as 70 diseases in open-access papers, as found by Europe PMC text mining. Sharing a sentence is not in itself a finding about the gene and the disease. The quoted sentences say what the papers report.
breast carcinoma (11 papers, 2013 to 2024). "SPAG9 (sperm-associated antigen 9) is an identified target of miR-9-5p, and has been shown to enhance Taxol resistance in breast cancer." (PMID 38785786, 2024). "Sperm-associated antigen 9 (SPAG9) mRNA and protein expression was found in the cytoplasm of all examined breast cancer cells, including TNBC cells." (PMID 34359776, 2021). "Our study provides an association between SPAG9 expression and its potential role in breast cancer, and thus lays a foundation for developing a promising therapeutic target for triple-negative breast cancer." (PMID 24330581, 2013). "SPAG9 expression was shown to be associated with epithelial ovarian cancer, renal cell carcinoma, breast cancer, cervix cancer, thyroid cancer and colorectal carcinoma." (PMID 24349057, 2013). "Recently, we reported an association of a novel cancer testis (CT) antigen, sperm-associated antigen 9 (SPAG9) expression in breast cancer clinical samples, indicating its potential role in carcinogenesis." (PMID 24330581, 2013). "Interestingly, we also demonstrated an association of SPAG9 immuno-reactivity score (IRS) in early grades of breast cancer patients." (PMID 24330581, 2013). "SPAG9 has been proposed as a biomarker for diagnosis in carcinoma of the breast, endometrium, cervix, thyroid, and colon, and has been proposed to be involved in the tumorogenesis and growth." (PMID 29472933, 2018). "Further, surface localization of SPAG9 protein was detected in all four breast cancer cells as demonstrated by FACS analysis." (PMID 24330581, 2013). "Our RT-PCR results confirmed SPAG9 mRNA expression in all breast cancer cells which was further validated for protein expression by Western blotting and IIF." (PMID 24330581, 2013). "In this context, we investigated SPAG9 expression in breast cancer cells of different histological subtypes, harboring different hormone receptor." (PMID 24330581, 2013). "In the present study, we investigated the SPAG9 expression in different breast cancer cell line models of different hormone receptor status and different subtypes." (PMID 24330581, 2013). "Further, IIF results showed that SPAG9 was predominantly localized in the cytoplasm of breast cancer cells." (PMID 24330581, 2013). "All breast cancer cell lines evaluated displayed higher levels of SPAG9 expression, compared to control normal mammary cells." (PMID 24330581, 2013). "Yet, in other cancers, we reported similar pattern of SPAG9 expression in breast cancer in early stages and grades." (PMID 24349057, 2013). "FACS analysis clearly showed the displacement of fluorescence intensity on the X-axis in breast cancer cells probed with anti-SPAG9 polyclonal antibody indicating SPAG9 surface localization in MCF-7, MDA-MB-231, BT-474 and SK-BR-3 cells." (PMID 24330581, 2013). "Further, ablation of SPAG9 expression resulted in reduction in the tumor growth of human breast cancer xenograft in nude mice in vivo." (PMID 24330581, 2013). "Recently, sperm associated antigen 9 (SPAG9) has been shown to be expressed in various cancer types such as epithelial ovarian cancer (EOC-90%), renal cell carcinoma (RCC-88%), colorectal cancer (74%), breast cancer (88%) and cervical cancer (82%)." (PMID 34493268, 2021). "Moreover our recent studies on well characterized CT antigens, SPAG9 and AKAP4 have shown their association with breast cancer cases." (PMID 27658496, 2016). "Therefore, in this regard we investigated the involvement of a well characterized CT antigen, SPAG9 in breast cancer using various breast cancer cell line models." (PMID 24330581, 2013). "Nucleotide sequencing confirmed the SPAG9 mRNA sequence in all breast cancer cells." (PMID 24330581, 2013). "Furthermore we also demonstrated that SPAG9 expression was higher in all breast cancer cell compared to normal mammary epithelial cells." (PMID 24330581, 2013). "Our data revealed that SPAG9 mRNA and protein expression was detected in all breast cancer cells." (PMID 24330581, 2013).
breast carcinoma (continued). "In addition, humoral immune response against SPAG9 was also observed in 80% of early stages and low-grade breast cancer patients." (PMID 23451156, 2013). "Further, our studies demonstrated SPAG9 expression in 88% of breast cancer patients." (PMID 23451156, 2013). "SPAG9 was also shown to be anchored on the plasma membrane of breast cancer cells." (PMID 24330581, 2013). "Furthermore, knockdown of SPAG9 expression in vivo in nude mice also showed reduction in tumor growth indicating its important role in breast cancer." (PMID 24330581, 2013). "FACS analysis revealed distinct SPAG9 surface localization in breast cancer cells." (PMID 24330581, 2013). "SPAG9 mRNA and protein expression was detected in all breast cancer cells." (PMID 24330581, 2013). "Gene silencing approach was employed to study the association of SPAG9 with early spread and metastasis in highly aggressive triple-negative MDA-MB-231 breast cancer cells which may lead to new therapeutic strategies." (PMID 24330581, 2013). "In addition, in vivo xenograft studies further strengthen the role of SPAG9 in breast cancer." (PMID 24330581, 2013). "A number of the identified CD47-dependent genes including MBP1, TBL1XR1, girdin, cyclin D1, CDC27, SPAG9, and JAK1 have reported functions in breast cancer progression." (PMID 26840086, 2016). "We further assessed SPAG9 mRNA expression in normal mammary epithelial cells, MCF7, MDA-MB-231, BT-474 and SK-BR-3 breast cancer cell lines by quantitative real-time PCR." (PMID 24330581, 2013). "Two of them, PATL1 and PRRC2B were discussed earlier; SENP7 is a marker of poor prognosis in colon cancer; SPAG9 is expressed in a variety of malignancies and regulated by QKI in lung cancer; UBR5 promotes postsurgical breast cancer lung metastases, and NSD1 exerts tumor suppressive functions." (PMID 39664813, 2024). "In addition, relative qPCR data demonstrated 20 to 52 folds higher expression of SPAG9 mRNA in MCF-7, MDA-MB-231, BT-474 and SK-BR-3 breast cancer cells as compared to normal mammary epithelial cells." (PMID 24330581, 2013). "In conclusion, to the best of our knowledge, this is the first report where we have put forth an evidence of potential role of SPAG9 in cellular growth, migration, invasion and colony forming ability in highly aggressive triple-negative MDA-MB-231 breast cancer cells." (PMID 24330581, 2013). "In contrast, it is important to mention that in our study, SPAG9 expression was detected in all breast cancer cells, independent of their hormone receptor status or HER2 expression pattern." (PMID 24330581, 2013). "Further, our FACS data revealed that SPAG9 protein was also localized on the plasma membrane of MCF-7, MDA-MB-231, BT-474 and SK-BR-3 breast cancer cells, indicating its putative use in development of immunotherapeutic target for breast cancer treatment." (PMID 24330581, 2013). "In addition, 88% breast cancer specimens showed SPAG9 expression independent of tumor stages and grades." (PMID 24330581, 2013). "Thus, our RT-PCR results indicated that SPAG9 gene is expressed in all breast cancer cells independent of their hormone receptor status or subtypes." (PMID 24330581, 2013).
prostate carcinoma (9 papers, 2014 to 2025). A carcinoma that arises from epithelial cells of the prostate gland. "Expression of SPAG9 in epithelial ovarian, breast, cervix, and thyroid cancer, as well as in renal cell and colorectal carcinoma was linked to tumor progression and migration, whereas the role of SPAG9 in prostate cancer remained unknown." (PMID 25504435, 2014). "A direct role for aberrant SPAG9 was identified in diverse human cancers such as Kaposi’s sarcoma, gastric cancer, prostate cancer, thyroid carcinoma, liver cancer, and bladder transitional cell carcinoma." (PMID 35227274, 2022). "Our analysis of the reported expression pattern of 152 humane prostate tissue samples revealed that both, PRK1 and SPAG9 were significantly overexpressed in prostate cancer tissue, but most importantly also in metastases compared to normal tissue." (PMID 25504435, 2014). "Immunohistochemistry performed on prostate cancer tissue and lymph node metastases sections showed similar distribution of PRK1 and SPAG9, indicating their relevance in prostate cancer progression." (PMID 25504435, 2014).
gastric cancer (7 papers, 2015 to 2025). A primary or metastatic malignant neoplasm involving the stomach. "Previous study has reported that LINC00483 expression was enhanced and promoted gastric cancer cell proliferation via regulating miR-30a-3p and sperm-associated antigen 9 (SPAG9)." (PMID 32293550, 2020). "The relationships between lncRNAs and protein‐coding RNAs identified via the microarray study suggest that linc00483 is associated with SPAG9 in gastric cancer." (PMID 29761936, 2018). "For example, the over-expression of SPAG9 (sperm associated antigen 9) correlates with poor prognosis and leads to gastric cancer invasion and chemo-resistance." (PMID 26692821, 2015). "The Moreso, Pearson correlation assay showed that linc00483 and SPAG9 expression were strongly positively correlated in gastric cancer tissues (R = .6170, P < .01)." (PMID 29761936, 2018). "Here, we report that linc00483 promotes proliferation and inhibits apoptosis through upregulation of SPAG9 and activation of MAPKs in both an in vitro and in vivo gastric cancer model." (PMID 29761936, 2018). "Next, we examined SPAG9 expression in gastric cancer tissues and paired normal gastric tissues by RT‐qPCR (n = 48), and SPAG9 mRNA expression was higher in gastric cancer tissues than in the corresponding normal gastric tissues (P < .01)." (PMID 29761936, 2018). "Pearson correlation assay confirmed that miR‐30a‐3p, linc00483 and SPAG9 mRNA were strongly negatively correlated in gastric cancer tissues (R = −.6488, P < .0001, R = −.6133, P < .001)." (PMID 29761936, 2018). "Also, LINC00483 can modulate cell growth and apoptosis in gastric cancer by sponging miR-30a-3p to upregulate SPAG9 and activate MAPK pathway." (PMID 33483471, 2021). "Collectively, these results demonstrated that miR‐30a‐3p acts as an anti‐oncogene and plays an important biological function that may correlate with linc00483 and SPAG9 in gastric cancer." (PMID 29761936, 2018). "Therefore, we can conclude that linc00483 mediates the function of SPAG9 and MAPKs in promoting proliferation and inhibiting apoptosis in gastric cancer." (PMID 29761936, 2018). "Our results revealed cross‐talk between linc00483 and SPAG9 mRNA via competition for miR‐30a‐3p, thus enhancing the expression of the miR‐30a‐3p target gene SPAG9, and then activating MAPKs to promote proliferation and inhibit apoptosis among gastric cancer cells." (PMID 29761936, 2018). "Furthermore, it restores SPAG9 expression, which is negatively regulated by miR‐30a‐3p, and actives MAPK signaling pathway in gastric cancer cells." (PMID 29761936, 2018).
lung carcinoma (6 papers, 2016 to 2024). "Analysis of SPAG9 and HLA-G expression in parental CRUK0748-XCL cells revealed that both SPAG9 and HLA-G are expressed in parental CRUK0748-XCL, signifying that HLA-G and SPAG9 are expressed in primary lung cancer cells with a high predisposition to BM." (PMID 36780531, 2023). "Sperm associated antigen 9 (SPAG9) is also overexpressed in lung cancer." (PMID 35574342, 2022). "Cancer testis antigen sperm‐associated antigen 9 (SPAG9) could distinguish lung cancer from normal controls (p < 0.001), and the level of the SPAG9 autoantibody in the sera of untreated patients was significantly higher than that in treated patients." (PMID 34288108, 2021). "Our findings demonstrate that targeting SPAG9 mitigates the ability of primary lung cancer cells to accumulate in the brain and establish mature brain lesions." (PMID 36780531, 2023). "SPAG9 antibody in serum appears to be related to the type of lung cancer, indicating its specificity to lung-related tissues." (PMID 33240937, 2020). "Additionally, the levels of SPAG9 autoantibodies in the serum of lung cancer patients are higher than in healthy controls." (PMID 35574342, 2022). "Previous research also showed that SPAG9 might act as an important promoter of tumor invasion via the SPAG9/JNK/MMP9 pathway in lung cancer." (PMID 26790956, 2016). "Thus, both SPAG9 and SPAG9 autoantibodies can be used in lung cancer diagnosis." (PMID 35574342, 2022). "Several CTAs, such as XAGE, SPAG9 and AKAP4, have been considered as biomarkers for the diagnosis and prognostic prediction of lung cancer." (PMID 35574342, 2022).
ovarian carcinoma (5 papers, 2016 to 2025). A malignant neoplasm originating from the surface ovarian epithelium. "In vitro experiments have shown that SPAG9 knockout is associated with ovarian cancer resistance to paclitaxel‐induced cell death." (PMID 38896069, 2024). "SPAG9 silencing in combination with paclitaxel treatment synergistically inhibited ovarian cancer cell viability, and SPAG9 depletion in ovarian cancer xenograft mouse models significantly reduced tumor growth." (PMID 38596293, 2024). "Although the amplification of SPAG9/JLP was observed only in 3 % of the cases analyzed, the increased expression correlates with the decreased disease-free survival of ovarian cancer patients." (PMID 27655714, 2016). "Using specific antibodies that only recognize the N-terminal epitope of JLP, which is absent in SPAG9 and JIP4, our studies unequivocally demonstrate the overexpression of JLP in multiple ovarian cancer cells and cancer tissue." (PMID 27655714, 2016). "Antibodies to SPAG9 can be detected in 67% of serum samples of ovarian cancer." (PMID 38896069, 2024). "Potential tumor promoting role for JLP is further substantiated by the cBioPortal analysis of TCGA dataset of ovarian cancer tissue, which indicates that the increased expression of SPAG9/JLP correlates with a reduction in the disease free survival of ovarian cancer patients." (PMID 27655714, 2016). "In addition, SPAG9 is an immunogenic CTA in ovarian cancer patients." (PMID 38896069, 2024). "Similarly, TEX19, SPAG9, HSP70‐2, and AKAP4 can promote the invasion and metastasis of ovarian cancer, and the downregulation of these genes can significantly inhibit the migration and invasion ability of ovarian cancer cells." (PMID 38896069, 2024). "The members of the CTA family in ovarian cancer mainly include MAGE, GAGE 1/2, LAGE‐1, NY‐ESO‐1, SSX, CT45, and TRAG‐3, which belong to the CT‐X antigen, and AKAP3/4, BAGE, BORIS, OY‐TES‐1(CT23), PRAME, PIWIL, HSP70‐2, SPAG9, and SP17, which belong to non‐X CT antigen." (PMID 38896069, 2024). "This, in turn could contribute significantly to the aggressive progression of ovarian cancer - even in the absence of SPAG9/JLP gene amplification." (PMID 27655714, 2016). "Using antibodies that do not cross-react with JIP4 or SPAG9, we carried out an immunohistochemical analysis to monitor the expression of JLP in ovarian cancer tissue." (PMID 27655714, 2016).
cervical cancer (4 papers, 2013 to 2022). A primary or metastatic malignant neoplasm involving the cervix. "Recently, SPAG9 was shown to be associated with cervical cancer which also showed that majority of the patients generated humoral response against SPAG9 protein suggesting that SPAG9 is a highly immunogenic protein." (PMID 34493268, 2021). "Recently, we reported the expression of sperm associated antigen 9 (SPAG9) that is associated with various types of malignancies including cervical cancer." (PMID 34493268, 2021). "In addition, SPAG9 was also shown to be associated with cellular proliferation, migration and invasion in squamous cell carcinoma-derived cervical cancer (SiHa), renal cell carcinoma (Caki-1) and colon cancer (COLO 205 and HCT 116) cell line models, respectively." (PMID 24330581, 2013). "For example, NEAT1, sponging miR-9-5p, enhances the resistance of anaplastic thyroid carcinoma cells to cisplatin by regulating SPAG9 expression, promotes the growth of cervical cancer cells, and regulates pulmonary fibrosis." (PMID 35038133, 2022). "In the current study, our results confirmed the expression of SPAG9 protein] in all histotypes and grades of cervical cancer patients who were included for this investigation." (PMID 34493268, 2021). "SPAG9 protein expression was probed in 12 cervical cancer patients using IHC." (PMID 34493268, 2021). "We examined the recombinant human SPAG9 (rhSPAG9) as an antigenic source for generating efficient DCs to stimulate CD4+ and CD8+ T cell responses for future DCs-based vaccine trials in cervical cancer patients." (PMID 34493268, 2021).